ATF2 (activating transcription factor 2)
Diseases named in the same sentence as ATF2 in open-access papers (continued):
Sharing a sentence is not in itself a finding about the gene and the disease.
breast cancer (36 papers, 2009 to 2025). A primary or metastatic malignant neoplasm involving the breast. "ATF2 expression has also been reported to be associated with shorter survival of patients with mammary carcinomas." (PMID 23878598, 2013). "Since ATF2 plays a vital role in cellular proliferation and apoptosis, it is believed that it greatly affects the development of breast cancers." (PMID 37955015, 2023). "We suggest further research to elucidate the dual roles of ATF2 in breast cancer and potential therapeutic therapies for its treatment." (PMID 37955015, 2023). "ATF2 has been suggested to modulate estrogen receptor (ER) expression and activity, potentially affecting tamoxifen sensitivity in breast cancer cells." (PMID 37955015, 2023). "In this narrative review, we investigate several studies that have been published about the role of ATF2 in breast cancer." (PMID 37955015, 2023). "Overall, this review highlights the significance of ATF2 at the molecular level in breast cancer progression and underscores the need for continued investigation in this area." (PMID 37955015, 2023). "There is still uncertainty regarding the exact role of ATF2 in the development and outcome of breast cancer." (PMID 37955015, 2023). "The article implies that the four DNA-damaging agents activate JNK, p38, and extracellular signal-regulated kinase (ERK), thereby increasing phosphorylation and ATF2-dependent transcriptional activity in human breast cancer BT474 cells." (PMID 37955015, 2023). "Other research has found that the expression of ATF2 plays a role in improving the outcome of breast cancer." (PMID 37955015, 2023). "Recent study found ATF2 participated in the endocrine treatment resistance of breast cancer by modulating ER expression and activity." (PMID 35641966, 2022). "In the GSE145548 cohort, knockdown of ATF2 in breast cancer cells MCF7 resulted in the dramatic change of cuproptosis regulators (DLST, GCSH, PDHA1, LIPT1 and DLD)." (PMID 36733399, 2022). "Leptin can promote invasion and lung metastasis of breast cancer cells by activating the PI3K/Akt-ATF-2 signaling pathway." (PMID 34787047, 2021). "We previously showed that high expression of p-ATF2 (69/71) was associated with longer disease-free (DSS) and breast cancer-specific survival (BCSS) in ER-positive high-risk patients exposed to tamoxifen." (PMID 33198803, 2020). "Conversely, ATF2 exerts a tumor suppressor role in breast cancer and skin cancer, suggesting a tumor-specific characteristic of ATF2 function." (PMID 33298086, 2020). "This indicates that ATF2 plays an important role in regulating migration of tamoxifen-resistant breast cancer cells, compared to endocrine-sensitive MCF7 cells." (PMID 33198803, 2020). "Co-culture with malignant epithelial cells in primary human adipose fibroblasts obtained from breast cancer patients increased the levels of phosphorylated ATF2 (pATF2) at the promoter of the aromatase gene responsible for oestrogen synthesis." (PMID 33198803, 2020). "Together, these findings are strongly supportive of a role for ATF2 as an oncogene in breast cancer." (PMID 33198803, 2020). "Activating transcription factor-2 (ATF2), a member of the leucine zipper family of DNA binding proteins, has been implicated as a tumour suppressor in breast cancer." (PMID 33198803, 2020). "Several studies reported that v-src causes ATF2 and CREB to bind the CRE/ATF site of the cyclin D1 gene, leading to transcription of cyclin D1 in MCF7 human breast cancer cells." (PMID 33198803, 2020). "Protein expression of a large panel of MAPKs (JNK1/2, ERK, p38, C-JUN and ATF2 including phosphorylated forms) were assessed immunohistochemically in a large (n = 1400) and well-characterised breast cancer series prepared as tissue microarray." (PMID 27592113, 2016). "ATF2 has been reported to modify Cyclin B1 and Cyclin D1 levels to promote cell-cycle progression in several types of neoplasms, including cervical and breast cancer." (PMID 27377902, 2016).
breast cancer (continued). "For instance, ATF2 acts as a tumor suppressor in breast cancer by promoting the expression of the apoptosis-regulated gene GADD45α and suppressor gene Maspin." (PMID 27377902, 2016). "Secondly, the activating transcription factor 2 (ATF2) is also strongly involved in breast cancer studies and was removed by the NCA prior to the analysis." (PMID 26537518, 2015). "ATF-2 stimulates the expression of c-Jun, cyclin D, and cyclin A, and it is known to play a major oncogenic role in breast cancer, prostate cancer, and leukemia." (PMID 22852817, 2012). "Heterozygous Atf-2 mutant mice are highly prone to developing mammary tumors after long periods of latency because of dramatic reductions in the expression of Maspin, a mammary tumor suppressor gene, and Gadd45α, which is induced by hypoxic stress." (PMID 22380515, 2012). "Additionally, there are numerous ongoing clinical trials exploring the effect of targeting ATF2 pathways and mechanisms on the outcome of breast cancers, some of which we have discussed." (PMID 37955015, 2023). "In this review, we explored the topic of ATF2 and its role in the development of breast cancer." (PMID 37955015, 2023). "In addition, another study found that ectopic expression of ATF2 inhibited ferroptosis induced by a bromodomain and extraterminal domain protein inhibitor in human breast cancer cells by upregulating NRF2." (PMID 36765266, 2023). "In conclusion, our review has revealed several key insights, including that ATF2 may have dual functions in the development of breast cancer." (PMID 37955015, 2023). "In this review, we will focus on the role of ATF2 in the development of breast cancer." (PMID 37955015, 2023). "According to a recent study, Leptin could induce IL-18 expression in both TAMs controlled by NF-B/NF-B1 and breast cancer cells controlled by PI3K-AKT/ATF-2 signaling, which, eventually, leads to the invasion and metastasis of breast cancer cells." (PMID 36119049, 2022). "Fractionation western blotting analysis using mitochondrial and nuclear fractions from mammary tumors indicated that the ATF2 protein was enhanced in the tumors from ATF2T52A transduction cells and almost undetectable in the tumors derived from the ATF2-depleted cells." (PMID 25852302, 2015). "ATF-2 regulates the transcription of Maspin via direct binding to the Maspin gene and Gadd45α transcription through interactions with two transcription factors, Oct-1 and NF-I, and the breast cancer tumor suppressor BRCA1." (PMID 22380515, 2012). "Breast cancer frequently develops in mutant mice heterozygous for the ATF-2 gene." (PMID 20953429, 2011). "This study also provides great insight into the role of ATF2 in endocrine treatment and drug resistance in human breast cancer cells, which may provide an important basis for other research to develop effective therapeutic solutions to treat drug-resistant cancers." (PMID 37955015, 2023). "The studies and clinical trials that are being conducted to understand the multifaceted role of ATF2 and its signaling pathways may provide valuable insight for developing efficient targeted therapeutic solutions to enhance the outcomes of breast cancer and overcome endocrine resistance." (PMID 37955015, 2023). "Furthermore, pATF2 has been shown to facilitate the transcription of MMP2, which increases migration in H-Ras-transformed MCF10A human breast epithelial cells indicating that ATF2 may play a role in breast cancer metastasis." (PMID 33198803, 2020). "However, the exact role of ATF2 in breast cancer is still unclear." (PMID 33198803, 2020). "Indeed IL-18 expression leads to invasion and metastasis of breast cancer cells through PI3K-AKT/ ATF-2 signaling, and it might be regulated through NF-κB/NF-κB1 signaling in TAMs43." (PMID 32695310, 2019). "In breast cancer patients, high expression of ATF-2 is positively correlated with the survival of patients, while patients with low expression of ATF-2 have worse postoperative effects." (PMID 35692887, 2022).
breast cancer (continued). "We knocked down ATF2 in TAMR, LCC2 and LCC9 tamoxifen-resistant breast cancer cell lines as well as the parental tamoxifen sensitive MCF7 cell line and investigated the effects on growth, colony formation and cell migration." (PMID 33198803, 2020). "ATF2 has been found to increase the transcription of matrix metalloproteinase 13 (MMP13), which may help facilitate breast cancer bone metastasis." (PMID 33198803, 2020). "Among them, ATF-2 demonstrated antiproliferative activity comparable to HER2 inhibitor lapatinib and significantly suppressed HER2 expression and activity, epidermal growth factor receptor (EGFR) activity, and cyclin-dependent kinase 6 (CDK6) expression in HCC1954 breast cancer cells." (PMID 41537091, 2025). "Several studies suggest that ATF2 may function as an oncogene, worsening the outcome of the disease, as it increases the transcription of genes such as MMP2, MMP13, cyclin A, and aromatase that contribute to the progression and metastasis of breast cancer." (PMID 37955015, 2023). "Activating transcription factor 2 (ATF2) is another protein with an oncogenic role in lung cancer and increases NRF2 expression following treatments with a group of drugs named BET inhibitors (BETi, with the ability to induce ferroptosis in breast cancer) in LUAD, leading to ferroptosis resistance." (PMID 34926310, 2021). "Additionally, ATF2 regulates the transcription of maspin and GADD45- α genes in mammary tumors." (PMID 26537518, 2015). "One member of the AP-1 protein family, activating transcription factor 2 (ATF2), has tumor suppressor activities in nonmalignant skin tumors and breast cancer." (PMID 25215281, 2014). "Importantly, FOXA1, ATF2, ATF3 and many other known key regulators in breast cancer could not be incorporated by any NCA algorithm because of the necessary conditions." (PMID 26537518, 2015).
colorectal cancer (17 papers, 2014 to 2025). A primary or metastatic malignant neoplasm that affects the colon or rectum. "Overexpression of ATF2 enhances growth, migration, and invasion in colorectal cancer cells through this mechanism." (PMID 39633985, 2024). "Due to only limited studies, the significance of ATF2 in colorectal cancer (CRC) is not well understood." (PMID 35838828, 2022). "Expression of Wnt-11 in colorectal cancer cell lines expressing low endogenous Wnt-11 inhibited β-catenin/Tcf activity and increased ATF2-dependent transcriptional activity." (PMID 31261741, 2019). "Additionally, Activating transcription factor 2 (ATF2) is known to participate in colorectal cancer by negatively regulating the transcription of miR-3913-5p through promoter binding." (PMID 40642075, 2025). "The ATF2/miR-3913-5p/CREB5 axis is considered a potential therapeutic target for colorectal cancer." (PMID 39633985, 2024). "Chen concluded that MJD1C can affect colorectal cancer metastasis by targeting ATF2." (PMID 35592424, 2022). "In colorectal cancer cells, SLC2A3 expression is regulated by the TGF-β/JNK/ATF2 signaling pathway, thus, increased SLC2A3 levels exacerbate the aggressiveness of colorectal cancer cells." (PMID 38778609, 2025). "ATF2 binds to the promoter region of GLUT3, enhancing EMT in colorectal cancer by inducing GLUT3 expression." (PMID 39633985, 2024). "The miRNA miR-3913-5p inhibits colorectal cancer cell proliferation, migration and invasion, in concert with its regulation of and by CREB5 and ATF2." (PMID 37816820, 2023). "Our demonstration of the activation of ATF2 mediated by TGF-β in human colorectal cancer (HCT116) cells is in agreement with several previous studies, implying the metastatic potential of elevated ATF2." (PMID 36009381, 2022). "To determine the precise molecular mechanism and the link between TGF-β and GLUT3 in colorectal cancer, we investigated the downstream signalings of the TGF-β pathway, JNK and the transcription factor ATF2." (PMID 36009381, 2022). "Several signaling pathways have been explored, and among them, the AKT/β catenin pathway is triggered by ROS to induce apoptosis in colorectal cancer cells, similarly to the JNK/ATF2 pathway in NB4 cells, all of which belong to the MAPK family." (PMID 34638987, 2021). "In Affymetrix primeview human GeneChip array, we found six upregulated genes (STAT1, ATF2, TNFRSF10B, TGFBR2, BAX, and SQSTM1) and two downregulated genes (SLC4A7 and CD274) related to apoptosis and proliferation of colorectal cancer cells after hsa_circ_0064559 knockdown." (PMID 37280630, 2023).
prostate carcinoma (16 papers, 2010 to 2025). A carcinoma that arises from epithelial cells of the prostate gland. "Together our findings demonstrate that at least some prostate cancer-associated mutants of SPOP are defective in regulating ATF2 protein." (PMID 29996942, 2018). "Strikingly, prostate cancer-associated mutants of SPOP are defective in promoting ATF2 degradation in prostate cancer cells and contribute to facilitating prostate cancer cell proliferation, migration and invasion." (PMID 29996942, 2018). "To examine the effect of SPOP mutations on ATF2 protein levels in specimens from individuals with prostate cancer, we analyzed ATF2 protein levels in a cohort for which a total of 90 primary prostate tumor samples were available." (PMID 29996942, 2018). "Cytoplasm location to p-Elk-1 and p-ATF-2 could be mutant form that present altered functions and may be associated with the prostate cancer development." (PMID 20078866, 2010). "Therefore, we speculated that prostate cancer-associated SPOP mutations may cause dysfunctions in regulating ATF2 protein levels." (PMID 29996942, 2018). "Impaired binding of SPOP mutants to the ATF2 protein leads to reduced proteasomal degradation and subsequent accumulation of ATF2 in prostate cancer cell lines and specimens." (PMID 40771930, 2025). "Decreased PHF8 leads to the enrichment of H3K9me2 in the promotor region of activating transcription factor 2 (ATF2) and permits its transcription, thereby inhibiting the proliferation of prostate cancer cells." (PMID 39311138, 2024). "Accumulating evidence supports the notion that ATF2 plays a critical role during prostate cancer initiation and progression." (PMID 29996942, 2018). "Taken together, the study provides novel insights into the aberrant regulation of ATF2 in prostate cancer, showing that ATF2 is an important mediator of SPOP inactivation-induced cell proliferation, migration and Invasion." (PMID 29996942, 2018). "Taken together, these data demonstrate that the SPOP-CUL3-RBX1 E3 ubiquitin ligase complex regulates ATF2 protein stability through ubiquitin-dependent proteasomal degradation in prostate cancer cells." (PMID 29996942, 2018). "Analysis of samples from normal prostate tissue, benign prostatic hyperplasia and prostate cancer revealed that phosphorylated ATF2 is overexpressed in benign prostatic hyperplasia and, much higher, in prostate tumors." (PMID 29996942, 2018). "Activation of p38 MAPK is also important for the malignant phenotype in prostate cancer cells, and this is due in part to activation of the transcription factor ATF2 by phosphorylation." (PMID 22135748, 2011). "In another study, however, UCA1 was confirmed may function as a ceRNA to reversely regulate ATF2 expression in prostate cancer, which is an interesting phenomenon worth further investigating." (PMID 36200182, 2022). "Previous studies have reported that UCA1 and ATF2 showed a positive correlation in prostate cancer." (PMID 36200182, 2022). "In addition, Wnt-11 increased ATF2-dependent gene reporter activity in both cell lines, a similar extent as has been observed in prostate cancer cell lines." (PMID 31261741, 2019). "We hypothesized that some prostate cancer-associated mutations in SPOP might disrupt the interaction between wild-type SPOP and ATF2." (PMID 29996942, 2018). "Development of therapeutic approaches for targeting aberrant ATF2 activation could be a viable treatment in prostate cancer." (PMID 29996942, 2018). "In prostate cancer cells, Wnt-11 and several FZDs activated ATF2-dependent transcription." (PMID 29717114, 2018). "In this study, we demonstrated that SPOP forms a functional CUL3-SPOP-RBX1 E3 ubiquitin ligase complex that targets ATF2 for ubiquitination and proteasomal degradation in prostate cancer cells, contributing to facilitating prostate cancer cell migration and invasion." (PMID 29996942, 2018). "ATF2 aggregation can be observed in the cytoplasm of prostate cancer rafter radiotherapy." (PMID 27941998, 2016).
prostate carcinoma (continued). "To test this hypothesis, we generated a series of Myc-tagged prostate cancer-associated mutants of SPOP, including Y87C, Y87N, F102C, S119 N, F125 V, K129E, W131G, W131C, F133 L, F133 V and K134 N, and examined their capacity to promote ATF2 degradation." (PMID 29996942, 2018). "Percentages of patients showing positive immunohistochemical reactions to p-ELK-1, ATF-2, p50 and p65 in normal prostate (NP), benign prostatic hyperplasia (BPH) and prostatic carcinoma (PC) and average optical densities of immunostaining in positive patients." (PMID 20078866, 2010). "In prostate cancer cells, gene reporter assays have been used to show that Wnt-11 increases non-canonical Wnt signaling, measured using an ATF2-dependent luciferase reporter, and inhibits canonical Wnt (β-catenin/Tcf-dependent) signaling." (PMID 31261741, 2019). "TMPRSS4 induced Slug, an epithelial-mesenchymal transition (EMT)-inducing transcription factor, and cyclin D1 through activation of AP-1, composed of c-Jun and activating transcription factor (ATF)-2, which resulted in enhanced invasion and proliferation of PC3 prostate cancer cells." (PMID 27385093, 2016). "FZD4 mRNA levels were upregulated in prostate tumor datasets but FZD4 silencing did not affect Wnt-11 activation of ATF-2-dependent transcription and FZD4 did not colocalize with Wnt-11, so FZD4 is unlikely to transduce Wnt-11 signals in prostate cancer." (PMID 29717114, 2018).